FABP5 (fatty acid binding protein 5)
Diseases named in the same sentence as FABP5 in open-access papers (continued):
Sharing a sentence is not in itself a finding about the gene and the disease.
psoriasis (40 papers, 2005 to 2026). An autoimmune condition characterized by red, well-delineated plaques with silvery scales that are usually on the extensor surfaces and scalp. "Machine learning pinpointed MPHOSPH6, ENO1, MKI67, and FABP5 as lactylation-related biomarkers for psoriasis, with ROC curves confirming their strong diagnostic capabilities." (PMID 41909697, 2026). "FABP5 (epidermal FABP, keratinocyte FABP, cutaneous FABP, C-FABP), or psoriasis-associated FABP (PA-FABP), plays crucial roles in fatty acid binding, trafficking, lipid metabolism, and cell growth." (PMID 41149452, 2025). "FABP5, also known as epidermal or psoriasis-associated FABP, was initially identified in the psoriatic epidermis, hence its name." (PMID 40560938, 2025). "Elevated FABP5 levels in psoriatic skin contribute to the recruitment of neutrophils, which is a hallmark of psoriasis." (PMID 38892253, 2024). "The random forest algorithm further identified 28 genes significantly associated with psoriasis, including FABP5, CD47, and UBE2F." (PMID 38596682, 2024). "Overexpression of FABP5 has been observed in psoriatic tissue and is even called psoriasis-associated FABP (PA-FABP)." (PMID 34207318, 2021). "FABP5 is also called psoriasis-associated FABP (PA-FABP), which reflects its already proven links with this dermatosis." (PMID 27864793, 2017). "The FABP5 gene encodes the epidermal fatty acid binding protein and has been found to be upregulated in psoriasis tissue." (PMID 23349676, 2013). "Fatty acid binding protein 5 (psoriasis-associated, FABP5), found in epidermal cells, was first identified to be up-regulated in psoriasis keratinocytes." (PMID 22673103, 2012). "Multiple studies have reported that aberrant expression of Fabp5 under pathological conditions is associated with various diseases, including metabolic disorders, psoriasis, Alzheimer's disease, and malignant tumors, indicating its potential for clinical applications." (PMID 41550058, 2026). "We hypothesize that FABP5 may play a role in the pathogenesis of psoriasis by affecting lipid metabolism and causing TRM cell dysfunction." (PMID 38596682, 2024). "FABP-5 has been suggested as a marker of metabolic complications and, as psoriasis is tightly associated with MS, it could be proposed as such a marker in this group of patients." (PMID 36144237, 2022). "Likewise, the psoriasis and wounding associated factor, Fatty acid binding protein 5 (FABP5), showed normal weak suprabasal IFE expression in WT and “early” phenotype Krt76tm1a/tm1a mice which increased dramatically when wounds developed in “late” phenotype Krt76tm1a/tm1a mice." (PMID 25340345, 2014). "Inhibitors of FABP5 or downregulation of FABP5 expression can significantly improve inflammation and lipid metabolism in psoriasis." (PMID 40560938, 2025). "FABP5 alone lacks specificity as a biomarker for psoriasis, but its combination with KLRB1 enables differentiation from other skin diseases." (PMID 38596682, 2024). "These correlations provide insights into the interactions between FABP5, KLRB1, and T cells, contributing to our understanding of the underlying immunological mechanisms in psoriasis and the effects of different therapeutic interventions." (PMID 38596682, 2024). "The novel topical drug VX-509 also has shown efficacy in diminishing psoriasis inflammation by targeting the STAT3/FABP5 pathway." (PMID 38596682, 2024). "Recent studies suggest a potential little-known role for FABP5 in psoriasis pathogenesis, which contributes to the understanding of its involvement in various diseases." (PMID 38892253, 2024). "Our study analyzed the impact of DC-T cell crosstalk in psoriasis, elucidated the characterization of two biomarkers, FABP5 and KLRB1, in psoriasis, and highlighted the promise and value of tofacitinib in psoriasis therapy targeting DCs." (PMID 38596682, 2024).
psoriasis (continued). "Quantitative data from HALO revealed significantly higher mean values of positive cytoplasmic percentage for KLRB1 (33.24) and FABP5 (55.47) in the psoriasis group compared to the control group (9.932 and 14.30, respectively)." (PMID 38596682, 2024). "The substantial evidence suggests an elevation in FABP5 and KLRB1 expression in psoriasis, with a more pronounced trend in FABP5 than in KLRB1." (PMID 38596682, 2024). "FABP5 is also known as epidermal FABP (E-FABP), cutaneous fatty acid-binding protein (C-FABP), psoriasis-associated FABP (PA-FABP), keratinocyte FABP (K-FABP), intracellular lipid-binding protein (iLBP), and mal-1." (PMID 35445019, 2022). "Upregulated FABP5 expressions in epidermal LCs of human psoriatic lesions and psoriasis-like murine skin tissues were verified by immunohistofluorescence analysis." (PMID 35801590, 2022). "Previous studies demonstrated that FABP5 is tightly involved in the development of psoriasis through regulating keratinocyte differentiation and mediating systemic metabolic disturbances." (PMID 35801590, 2022). "FABP5 was initially detected and cloned in psoriasis, a hyperproliferative skin disease characterized by abnormal differentiation and disordered lipid metabolism." (PMID 35445019, 2022). "Based on psoriasis activity FABP5 concentration in patients with severe form of the disease (PASI > 20) was higher compared to the mild group (PASI < 10) (P < 0.001)." (PMID 34131888, 2021). "It is difficult to verify if the observed changes in FABP5 levels are related to UV-therapy or to the improvement of psoriasis." (PMID 34131888, 2021). "FABP5 is a potential marker of psoriasis, its severity and clinical outcome after therapy with NB-UVB." (PMID 34131888, 2021). "Similar to psoriasis, FABP5 is mainly localized to the nuclei of suprabasal KCs, suggesting efficient local generation of PPARδ ligands to sustain the activation of PPARδ." (PMID 34298981, 2021). "So far, in psoriasis the role of only one FABPs isoform—epidermal fatty acid binding protein (E-FABP, FABP5) has been more widely documented." (PMID 30993401, 2019). "FABP5 is predominantly expressed in keratinocytes and actively proliferating tissue, such as that of psoriasis." (PMID 30061793, 2018). "Initially identified in psoriasis, FABP5 is unique to keratinocytes, is a key factor in keratinocyte differentiation, and interacts with other proteins found at altered abundances in our study." (PMID 26608071, 2015). "Through its mediation of lipid signaling, FABP5 has been shown to play a role in inflammatory and metabolic diseases including psoriasis, insulin resistance, obesity, and atherosclerosis." (PMID 25779666, 2015). "FABP5 (also epidermal FABP, keratinocyte FABP, psoriasis-associated FABP, and mal1), was first identified in psoriatic lesions, and further characterized in the epidermis." (PMID 25779666, 2015). "DEGPs provide a high-confidence molecular fingerprint of psoriasis and, as expected, we confirmed changes in mRNA and protein abundance for select DEGPs (FABP5 and SERPINB4) using RT-PCR and immunohistochemistry." (PMID 26251673, 2015). "While the overall differentiation of keratinocytes in late phenotype Krt76tm1a/tm1a dorsal skin was mostly normal, the hyperplasia, immune infiltrate and IFE expression of KRT6 and FABP5, were reminiscent of the hyperproliferative skin disorder, psoriasis." (PMID 25340345, 2014). "Conversely, negativity for either FABP5 or KLRB1 could indicate a protective factor against psoriasis." (PMID 38596682, 2024). "We identified unique expression profiles of KCs and DCs, further explored the importance of altered DC function in the development and progression of psoriasis, and identified two key genes, FABP5 and KLRB1, from the initially predicted 50 genes by a machine learning approach." (PMID 38596682, 2024). "The elevation of FABP5 in the psoriasis group is more pronounced." (PMID 38596682, 2024).
psoriasis (continued). "FABP5 interacts with VCP, which is a crucial player in NF-κB activation, and their silencing inhibits NF-κB signaling and neutrophil chemotaxis, suggesting a role in the molecular mechanisms underlying psoriasis pathogenesis." (PMID 38892253, 2024). "Conversely, FABP5 averaged 4.409 in psoriasis and only 0.1871 in the normal group." (PMID 38596682, 2024). "Moreover, KLRB1 and FABP5 expression in HaCaT cells, an in vitro model of psoriasis induced by M5, was 1.93-fold and 4.158-fold higher than the control group, respectively." (PMID 38596682, 2024). "FABP-1 and FABP-5 may become potential markers of metabolic complications and inflammation in psoriasis." (PMID 36144237, 2022). "In addition to psoriasis, FABP5 is also involved in atopic dermatitis (AD), radiation-induced skin fibrosis, and skin tumor development, as a biochemical marker in the skin’s horny layer." (PMID 35445019, 2022). "Present results may indicate that elevated serum FABP5 represents another link between psoriasis MS and cardiovascular comorbidities." (PMID 34131888, 2021). "The expression of FABP5 parallels that of PPARδ in psoriasis and atopic dermatitis." (PMID 34298981, 2021). "Additionally, the influence of narrowband—ultraviolet B (NB-UVB) treatment of psoriasis on FABP5 serum concentration have been investigated." (PMID 34131888, 2021). "The expression of FABP5 parallels that of PPARδ at both the mRNA and protein levels in psoriasis." (PMID 34298981, 2021). "A few papers have shown only the importance of FABP5 in psoriatic keratinocyte differentiation proving disturbances in fatty acid metabolism in the lesions but also in the uninvolved skin of patients with psoriasis." (PMID 27864793, 2017). "Fabp5 is a member of the fatty acid-binding proteins which binds free fatty acids and regulates lipid metabolism and transport; it was first identified as being upregulated in psoriasis tissue." (PMID 23710285, 2013). "Consequently, FABP5 may link psoriasis and MetS, although further investigation is required to investigate the underlying mechanisms." (PMID 38596682, 2024). "Moreover, the up-regulation of FABP5 may be partially involved in the alteration of the differentiation mechanism in psoriasis." (PMID 35445019, 2022). "The underlying mechanism of the association of FABP5 and psoriasis is not clear yet, but one of the possible explanation is role of the adaptive immune system, particularly of Th1 and Th17 lymphocytes, which has been regarded as prominent in the immunopathogenesis of psoriasis." (PMID 34131888, 2021). "A few inflammatory genes that were shared with vulvar lichen sclerosis and psoriasis were S100A8, S100A9 and FABP5." (PMID 41438752, 2025). "Additional investigations are needed to explore the relationship and mechanisms of action between FABP5 and KLRB1 in psoriasis." (PMID 38596682, 2024). "The downstream pathways of FABP5 vary across various dermatologic diseases, and our team’s future research will concentrate on the detailed mechanistic examination of FABP5 and KLRB1 in psoriasis." (PMID 38596682, 2024). "The results demonstrated that FABP5 and KLRB1 were significantly upregulated in psoriasis skin tissues." (PMID 38596682, 2024). "Psoriasis, a disease that can be mediated by CD8+ TRM cells co-expressing CD8 and CD69, has detectable FABP5 protein expression in skin lesions." (PMID 38596682, 2024). "To investigate the relationship between FABP5, KLRB1, and T cells in psoriasis, we performed Pearson’s correlation analysis using data from a psoriasis cohort." (PMID 38596682, 2024). "To explore the correlation between FABP5 and KLRB1, we examined skin lesions from three psoriasis patients and three healthy controls using immunofluorescence double staining." (PMID 38596682, 2024). "To further verify the predictive effect of FABP5 and KLRB1, we conducted differential expression analysis in two independent psoriasis cohorts." (PMID 38596682, 2024).
psoriasis (continued). "Combined with the analysis of fluorescence intensity curves, we deduce a co-localization of KLRB1 and FABP5 in both psoriasis and normal skin tissues, elucidating the characteristics of KLRB1 and FABP5 in these contexts." (PMID 38596682, 2024). "In psoriasis patients, KLRB1 exhibited heightened expression in the stratum corneum and dermis, while FABP5 showed increased expression in the entire dermis and epidermis, as indicated by brownish-yellow coloration in corresponding immunohistochemistry images." (PMID 38596682, 2024). "Quantitative analysis further demonstrated a statistically significant elevation in FABP5 positivity (55.47 vs. 33.24) and KLRB1 positivity (14.30 vs. 9.932) in the psoriasis group (p-values 0.0253 and 0.0211, respectively)." (PMID 38596682, 2024). "Double positivity for FABP5 and KLRB1 was 14.91 in the psoriasis group and 2.389 in the control group, exhibiting a slightly lower yet statistically more significant tendency for elevation than the first two groups (p-value 0.0024)." (PMID 38596682, 2024). "Previous studies have correlated serum FABP5 with both the PASI score and the basic inflammatory index in psoriasis patients, indicating its potential as a marker for psoriasis severity and clinical outcomes post-treatment with NB-UVB." (PMID 38596682, 2024). "Tofacitinib demonstrates advantages in studying drugs targeting DCs, with elevated expression and co-localization of FABP5 and KLRB1 in psoriasis." (PMID 38596682, 2024). "To validate these findings, we performed gene expression analysis of scRNA-seq data, which confirmed the overexpression of FABP5 and KLRB1 in cluster 1 DCs, reinforcing their potential role in psoriasis." (PMID 38596682, 2024). "In 2013, it started with a proteomics approach on keratome skin biopsies of psoriasis patients to discover alterations of psoriasis-related proteins S100A7, FABP5 and new potential biomarkers." (PMID 37175722, 2023). "Other studies revealed that FABP5 may represent mediators of and biomarkers for metabolic and cardiovascular disease in type 2 diabetes mellitus, thus it could play an important role and contribute to the development of cardiometabolic comorbidities in psoriasis." (PMID 34131888, 2021). "Present study group was free of liver diseases and the levels of transaminases were within the normal range so, based on present results, it is difficult to conclude about connection of FABP5 and NAFLD in psoriasis." (PMID 34131888, 2021). "Futhermore, the positive correlation between serum FABP5 concentration and PASI score before treatment was observed in patients with psoriasis (R = 0.42; p < 0.001)." (PMID 34131888, 2021). "The proteins identified by LC–MS/MS, including SFN, GSTP1, FABP5, S100A7, and RABP2, were also observed to be upregulated in psoriasis lesional tissues." (PMID 32817748, 2020). "FABP5 positivity coupled with KLRB1 negativity was observed at 40.56 in the psoriasis group and 11.91 in the normal group, while KLRB1 positivity with FABP5 negativity stood at 18.33 in the psoriasis group and 7.542 in the normal group." (PMID 38596682, 2024). "Furthermore, through the integration of the LASSO, random forest, and SVM-RFE algorithms, we identified FABP5 and KLRB1 as robust markers in psoriasis." (PMID 38596682, 2024). "The double positive of FABP5 and KLRB1 has higher specificity in the psoriasis group." (PMID 38596682, 2024). "Fatty acid binding protein 5 (FABP5) is elevated in psoriatic keratinocytes and could be involved in systemic metabolic disturbances in psoriasis." (PMID 34131888, 2021). "Although the mechanisms underlying the up-regulation of FABP5 in keratinocytes and psoriasis are not completely understood, previous studies suggest that FABP5 may have important roles in the regulation of fatty acid metabolism during keratinocyte differentiation in the pathogenesis of psoriasis." (PMID 30061793, 2018).
psoriasis (continued). "Serum FABP5 levels were similar between patients with psoriasis and controls, and did not reflect the skin condition." (PMID 27864793, 2017). "These include multiple canonical psoriasis-related proteins such as S100A7 (psoriasin) and epidermal fatty acid binding protein (FABP5), as well as alteration in expression of over 30 novel proteins, such as profilin 1, galectin-related protein, and glutaredoxin-1." (PMID 26362816, 2015). "FABP-5 was positively correlated with inflammatory parameters such as CRP and white blood cell counts, which may indicate that it can be used as one of the indicators of inflammation in psoriasis patients." (PMID 40560938, 2025). "Notably, FABP5 and KLRB1 exhibited up-regulation and co-localization in psoriatic skin tissues and M5-induced HaCaT cells, serving as potential biomarkers influencing psoriasis development." (PMID 38596682, 2024). "Thus, FABP5 and KLRB1 hold promise as significant biomarkers for psoriasis diagnosis." (PMID 38596682, 2024).